CRP (C-reactive protein)
Diseases named in the same sentence as CRP in open-access papers (continued):
Sharing a sentence is not in itself a finding about the gene and the disease.
coagulopathy (122 papers, 2008 to 2026). "Apparently, even if inflammation and coagulopathy are linked in COVID-19 patients, CRP and D-dimer effects on persistent lung damage are independent, acting through different causal pathways." (PMID 35277562, 2022). "A significant increase in the SOFA scores (P < 0.001), incidence of acidosis, coagulopathy, episodes of hypotension, and the serum creatinine, glucose, and CRP concentrations were associated with increases in the blood lactate levels." (PMID 30841912, 2019). "Any infectious disease mortality may be influenced by elevated blood levels of C-reactive protein, which raise the risk of coagulopathy and increase capillary permeability especially in hypertensive patients." (PMID 38709822, 2024). "Hence, dornase alfa treatment was associated with a suppression of circulating cf-DNA that correlated with a reduced risk for coagulopathy and a more sustained reduction in CRP." (PMID 39009040, 2024). "Based on such criteria, a previous study described that approximately one third of AML patients had coagulopathy consistent with DIC and coagulopathy was also associated with increased CRP levels, i.e., signs of an acute-phase reaction." (PMID 40565207, 2025). "The patients were selected to meet criteria reflecting severe illness with features of CSS (e.g., hyperferritinemia, coagulopathy, liver dysfunction, cytopenias, elevated C-reactive protein)." (PMID 40872807, 2025). "The significant elevation of GRP78 in patients with more pronounced inflammation (higher CRP), coagulopathy (higher D-dimer), and respiratory compromise (lower oxygen saturation) reinforces its potential as a clinically relevant biomarker." (PMID 41226352, 2025). "Elevated CRP and D-dimer levels are markers of systemic inflammation and coagulopathy, both of which are known to contribute to poor outcomes in critically ill patients." (PMID 39006555, 2024). "Against the background of progressively increasing respiratory insufficiency, the patient was transferred to high-flow oxygenation from 60 to 80 L/min, CRP increased to 28 mg/L, pronounced coagulopathy." (PMID 36883180, 2022). "Persistent fever, multi-lineage cytopenias, liver and kidney end-organ damage, coagulopathy, hypertriglyceridemia, hypofibrinogenemia, elevated CRP with relatively low ESR, and hyperferritinemia can all be seen in cases of HLH." (PMID 35207437, 2022). "Against the background of progressively increasing respiratory insufficiency, the patient was transferred to high-flow oxygenation from 25 to 80 L/min, the content of C‐reactive protein (CRP) increased to 45 mg/L, pronounced coagulopathy." (PMID 36883180, 2022). "Patients displayed high SARS-CoV-2 RNA levels (median of 106 copies/mL), laboratory markers of systemic inflammation and coagulopathy (because of elevated plasma levels of C-reactive protein [CRP] and D-dimer, respectively), and a case fatality ratio of 60%." (PMID 35459226, 2022). "This exacerbation of clinical symptoms is accompanied by an increase in acute phase proteins (CRP, ESR), coagulation disorders and cell lysis, which can be caused by hyper inflammation." (PMID 33726761, 2021). "In overt DIC patients and non-overt DIC patients, levels of inflammation-related indicators, such as PCT, high sensitivity CRP and IL-6 were significantly higher than those in non-coagulopathy patients." (PMID 33564286, 2021). "Organ dysfunction such as coagulopathy, liver failure, central nervous system dysfunction, and cardiac dysfunction can be seen with CRP, triglycerides, and D-dimer." (PMID 34773697, 2021). "In the present study, we also found that systemic inflammatory indicators C-reactive protein and IL-6 were persistent higher in coagulopathy patients than those in non-coagulopathy patients from the admission day to the coagulopathy onset." (PMID 33564286, 2021).
coagulopathy (continued). "By analyzing laboratory blood tests, we found that coagulopathy, myocardial injury, kidney injury, and increased CRP and IL-6 levels were exhibited more frequently in the severe group than in the non-severe group." (PMID 33693017, 2021). "Labwork showed hemoglobin of 5.9 g/dL, platelet of 55×109/L, coagulopathy, serum C-reactive protein (CRP) of 114.26 mg/L, and interleukin-6 (IL-6) of 146.69 pg/ml." (PMID 33604290, 2020). "High levels of biomarkers associated with inflammation (C-reactive protein, CRP, and IL-6) and coagulopathy (D-dimer and fibrinogen) are associated with increased risk of cardiovascular disease, increased cancer risks and mortality in the general population." (PMID 24330529, 2013). "Comparison between the two groups revealed that the S/T, CLI, CRP, coagulation disorders, blood glucose, and blood lactate levels were significantly higher in the CLS group than in the non-CLS group (P < 0.05), while the albumin level was significantly lower in the CLS group (P < 0.05)." (PMID 40692798, 2025). "Upon receiving laboratory test results for the fictitious patient with AHA (including elevated white blood cell counts and C-reactive protein [CRP] levels and prolonged aPTT), the proportion of participants who strongly suspected acquired coagulopathy increased slightly to 38.0%." (PMID 41220543, 2025). "This syndrome is characterized by the hyperactivation of tissue macrophages and the overproduction of inflammatory cytokines, such as IL-1, IL-6, and IL-8, and elevated levels of markers of inflammation, C-reactive protein (CRP), ferritin, and coagulation disorders involving D-dimer." (PMID 39767597, 2024). "Moreover, the cytokine storm co-exists with a massive increase in coagulopathies and acute phase reactants such as C-reactive protein (CRP) and serum ferritin which correlate with the severity of the disease." (PMID 37554293, 2023). "This review also emphasized the “STAT3 and Coagulopathy” with the production Tissue Factor induced by CRP which may have activated by STAT3 and prime the initial phase of coagulation." (PMID 35794133, 2022). "Multivariate logistic regression analysis showed that higher inflammation/coagulopathy/immunology responsive index (ICIRI=[c-reactive protein × fibrinogen × D-dimer]/CD8 T cell count) on admission (OR=345.151, 95% CI=23.014−5176.318) was associated with increased odds ratios for poor prognosis." (PMID 35310845, 2022). "COVID-19 infection induced a higher level of CRP (MD = 0.40; 95% CI: 0.16 to 0.64, P = 0.001; P < 0.00001 for heterogeneity) as well as coagulation disorders involving platelets, prothrombin time, activated partial thromboplastin time, and D-dimer (all P < 0.05)." (PMID 36338951, 2022). "Additionally, elevated levels of blood IL-6 and CRP occurred more frequently in patients with coagulopathy, and monocyte counts were significantly decreased when coagulopathy occurs." (PMID 33564286, 2021). "Coagulation changes in scrub typhus patients were characterized by an inflammation-induced coagulopathy, with coagulation activation, AT depletion, increases in the levels of proinflammatory cytokines and more pronounced CRP levels than in murine typhus patients." (PMID 22192733, 2012). "In addition, high IL-6, regardless of CRP value, associates with hemodynamic dysfunction characterized by reduced systolic and diastolic arterial pressure, coagulopathy, and hepatic and renal dysfunction." (PMID 35634339, 2022). "After adjustment for the sex, age, leukocyte count, C-reactive protein level, pathogens, amount of effusion, and presence of coagulopathy or shock, both impaired perfusion and HLs could favorably predict subsequent pneumatocele formation and surgical lung resection." (PMID 26086718, 2015). "It is characterized by elevated levels of inflammatory markers, particularly C-reactive protein (CRP), D-dimer, and erythrocyte sedimentation rate (ESR), as well as coagulopathy and organ dysfunction." (PMID 40843699, 2025).
coagulopathy (continued). "Laboratory tests: Lower hemoglobin and hematocrit; higher RDW (14.8% vs. 13.4%, p < 0.001); more pronounced coagulopathy (prolonged PT and elevated INR, both p < 0.01); lower albumin (33.2 vs. 38.9 g/L, p < 0.001); and higher C-reactive protein." (PMID 41458518, 2025). "Elevated C-reactive protein (CRP), ferritin, INF-γ and IL-10 levels accompanied by grade 3 coagulopathy with hypofibrinogenemia were subsequently observed." (PMID 35317863, 2022). "Endotype 1 patients had low levels of inflammatory markers (ferritin, IL-6, CRP, LDH), low infectious markers (WBC, procalcitonin), and low degree of coagulopathy (PTT, PT), while endotype 4 had higher levels of those markers." (PMID 34859018, 2021). "The degrees of CRP (inflammation), ISTH overt DIC score (coagulopathy) and nutrition status (albumin) on the first day were found to be important factors for PIICS development (standardized coefficient, 0.17, p < 0.001 and 0.09, p < 0.001, respectively)." (PMID 32824569, 2020). "Biomarkers of coagulopathy and inflammation, platelet counts, FDP, PT, α2-PI, AT III, plasminogen, and C-reactive protein were significantly different between the two groups." (PMID 28841902, 2017). "All cases at admission had elevated C-reactive protein (CRP) (mean level of 118 mg/L), and three patients (24%) had coagulopathy." (PMID 28743266, 2017). "Critical-type patients demonstrated significantly elevated inflammatory markers (neutrophils: 10.41 ± 6.23 × 109/L; CRP: 104.47 ± 29.18 mg/L) and coagulopathy (D-dimer: 5.21 ± 2.34 μg/ml) compared to non-critical cases." (PMID 40130249, 2025). "Blood tests revealed D-dimer 0.5 μg/mL, CRP 0.1 mg/dL, and platelets 18.1 × 104/μL, indicating no inflammation or coagulopathy." (PMID 41458771, 2025). "Laboratory data in both patients showed no significant systemic inflammation or coagulopathy (e.g., normal or only mildly elevated D-dimer and CRP), further weakening a mechanistic argument." (PMID 41458771, 2025). "Many factors, including SpO2, urea, CRP, PCT, SF, and fibrinogen levels, varied substantially between patients with long-term high and low levels of NAbs, and this was closely related to hypoxia, inflammation, and coagulation disorder." (PMID 35062284, 2022). "SOFA scores, CRP levels, neutrophil/lymphocyte ratios on days 5, 7, 10, 14 and 28 and the development of coagulopathy until the 28th day were not different between groups." (PMID 33907251, 2021). "CRP concentrations of the patients with coagulopathy were higher than patients without coagulopathy, but showing a downward trend after the occurrence of DIC." (PMID 33564286, 2021). "Furthermore, severe coagulopathy was significantly associated with higher peak levels of CRS-related markers of inflammation, LDH (p = 0.001) and ferritin (p = 0.006), but not with CRP." (PMID 41228344, 2025). "High levels of interleukin (IL)-6, C-reactive protein (CRP), and D-dimers have been observed in patients with COVID-19 ARDS, and the magnitude of the activation of the inflammatory cascade seems to be strongly correlated with the severity of coagulation disorders." (PMID 33401632, 2021). "Over all, no case of severe SIR with multiorgan failure and coagulopathy, but significant increases in body temperature, mean arterial blood pressure, and concomitantly increased serum levels of adrenaline, nor adrenaline or C-reactive protein (CRP) have been reported shortly after RF ablation." (PMID 22242035, 2011). "Endotype 1 patients had the lowest inflammatory markers (ferritin, IL-6, CRP, ESR, LDH), lowest infectious markers (WBC, procalcitonin), and lowest degree of coagulopathy (PT and PTT, but not significantly < endotype 2)." (PMID 34859018, 2021).
cerebrovascular disease (121 papers, 2008 to 2026). "Specifically, elevated CRP is associated with subclinical cerebrovascular disease and diffuse atherosclerosis, both of which impair physical function and contribute to frailty." (PMID 41295355, 2025). "In a study performed by Li et.al., lower lymphocyte count, indicating immunosuppression, together with higher CRP titer were associated with a higher risk of cerebrovascular diseases." (PMID 38999510, 2024). "As CRP is considered a marker of vascular disease, these results are in line with research that links vascular risk factors and markers of cerebrovascular disease with impairments in executive functioning." (PMID 33382815, 2020). "CRP, an acute phase protein, is vastly studied in geriatric populations and has been associated with an increased risk for cerebrovascular disease, Alzheimer’s disease, and vascular dementia." (PMID 32983153, 2020). "Furthermore, SII was superior to CRP as an inflammatory indicator of prognosis associated with cardiovascular and cerebrovascular diseases." (PMID 37440549, 2023). "CRP is associated with several cerebrovascular diseases and cardiovascular diseases." (PMID 32220241, 2020). "As a traditional inflammatory marker, CRP is an important predictor of the onset and prognosis of cardiovascular and cerebrovascular diseases." (PMID 40182426, 2025). "CRP, as a traditional inflammatory marker, plays an important role in predicting the onset and prognosis of cardiovascular and cerebrovascular diseases." (PMID 41035697, 2025). "Cox analysis showed the benefit of AZV+DXM in the subgroups of ≥65 years old, multiple organ dysfunction syndrome (MODS), cerebrovascular disease, C-reactive protein (CRP) ≥70mg/L, and D-dimer ≥1 μg/L." (PMID 39650837, 2024). "Elevated CRP is widely used to monitor acute stress conditions like cardiovascular or cerebrovascular diseases, infections, and surgical procedures." (PMID 39588332, 2024). "The patients with cerebrovascular diseases have a high inflammatory response and abnormal coagulation with elevated C-reactive protein and D-dimer levels." (PMID 35547415, 2022). "High-sensitivity C-reactive protein is an inflammatory marker with predictive value for cerebrovascular diseases." (PMID 36237188, 2022). "Previous studies have also found the correlation between Hs-CRP level and disability and neurological deficit in cerebrovascular diseases." (PMID 30477534, 2018). "In the study of Youssef and coworkers homocysteine and C-reactive protein (CRP) levels significantly correlated with prognosis of cerebrovascular disease according to NIHSS and mRS scores." (PMID 28424785, 2017). "With reference to cardiovascular and cerebrovascular disease, the prognostic value of C-reactive protein has become increasingly recognised." (PMID 25730322, 2015). "In short, there is need for more studies to clarify the exact role of CRP in cerebrovascular disease." (PMID 19400931, 2009). "Inflammation, the key regulator of CRP synthesis, plays an important role in atherothrombotic cardiovascular and cerebrovascular disease." (PMID 18764931, 2008). "Although VD results from cerebrovascular disease, studies have indicated that chronically elevated high sensitivity C-reactive protein (CRP) and the combination of elevated high sensitivity CRP and interleukin-6 due to inflammation are associated with an increased rate of VD." (PMID 40305494, 2025). "The variables that were used to construct the model include Charlson Comorbidity Index (CCI), APACHE II, Fracture, Cerebrovascular disease, Head injury, Delirium, MV, Benzodiazepines, Dexmedetomidine, Blood pH, Blood lactate, C-reactive protein (CRP), Hemoglobin." (PMID 38789502, 2024). "CRP, one of the acute response phase proteins, can reflect the level of inflammation in the body and the progress of cerebrovascular disease; TNF-α and IL-6 are proinflammatory factors, both of which can promote the chemotaxis and adhesion of inflammatory factors, and adversely affect patients." (PMID 35692885, 2022).
cerebrovascular disease (continued). "iii)In cardiovascular and cerebrovascular diseases (category “c”) and other diseases (category “e”), there was negative liner or non-liner associations between CRP and 25(OH)D generally." (PMID 32246038, 2020). "Furthermore, C-reactive protein, albumin and neutrophils were confirmed to have independent prognostic value in patients dying of cancer as well as cardiovascular and cerebrovascular disease." (PMID 25730322, 2015). "At present, it is believed that there is not enough evidence to recommend measurement of CRP in the usual evaluation of cerebrovascular disease risk in primary prevention." (PMID 24353532, 2013). "Cerebrovascular disease, respiratory complications, WBC count, albumin concentration, CRP concentration, and mGPS were detected as predictive factors of PAP." (PMID 41239633, 2025). "The predictive factors included in the prediction model were age, BMI, cardiovascular diseases, cerebrovascular diseases, neuropathy, thyroid diseases, fracture history, SII, PLR, C-reactive protein (CRP)." (PMID 38825605, 2024). "These variables included age, body mass index (BMI), cardiovascular diseases, cerebrovascular disease, neuropathy, thyroid disease, fracture history, SII, PLR, CRP." (PMID 38825605, 2024). "In the diabetic group, patients with high hs-CRP had a significantly higher incidence of smoking, CKD, ACS, prior MI, prior cerebrovascular disease, LMT involvement as well as lower LVEF on admission." (PMID 37081535, 2023). "C-reactive protein (CRP) is an important biomarker of inflammation and plays a pivotal role in predicting the clinical prognosis of cardiovascular and cerebrovascular diseases." (PMID 35659067, 2022). "However, when oxLDL/β2GPI further interacts with CRP through another site named oxPC, the pro-AS function of CRP/oxLDL/β2GPI complex was enhanced as our results showed, maybe due to the strong pro-inflammation function of CRP in AS of both cardiovascular and cerebrovascular diseases." (PMID 23531147, 2013). "Second, our final model included some predictors that aligned with previous studies, such as cerebrovascular disease, fracture, MV, APACHE II, CCI, and CRP, which were identified as candidate predictors by referring to related studies and literature review before the study started." (PMID 38789502, 2024). "In the liver, CRP production is triggered by IL-6, and elevated CRP has toxic effects on endothelial cells and raises the permeability of the BBB, thus enhancing the development of neurodegenerative and cerebrovascular diseases." (PMID 36675440, 2023). "C-reactive protein (CRP) is a nonspecific biomarker for cerebrovascular diseases, myocardial infectious inflammation, and cancer; however, the precise measurement of CRP is very challenging in POC settings." (PMID 37232930, 2023). "Furthermore, the prior observation that young age (<55 years), baseline CRP > 1 mg/dL, and no history of cerebrovascular disease were associated with European League Against Rheumatism remission at 6 months in RA patients treated with TCZ could not be confirmed in our study." (PMID 25922848, 2015).